G6PD (glucose-6-phosphate dehydrogenase)
Diseases named in the same sentence as G6PD in open-access papers (continued):
Sharing a sentence is not in itself a finding about the gene and the disease.
G6PD deficiency (continued). "G6PD deficiency is an X-linked disorder and thus deficient males and homozygous deficient women will exhibit the full extent of the deficiency whereas G6PD heterozygous women will have a range of G6PD activities from deficient to very normal G6PD activity." (PMID 32552815, 2020). "Since our study reports a high proportion of G6PD deficiency in patients of vivax malaria, epidemiologic and genotypic characterization may determine the rationale for G6PD deficiency screening of malaria patients receiving primaquine therapy." (PMID 33214970, 2020). "The data suggest that while a robust universal, assay-specific G6PD activity cutoff value can be established for diagnosis of severe G6PD deficiency (<30% normal enzyme activity), this approach is less robust for diagnosing intermediate G6PD deficiency." (PMID 32407380, 2020). "We are collecting data from different types of thalassemia genotypes with G6PD gene mutations, and next study may reveal the correlation between thalassemia and G6PD deficiency." (PMID 31793705, 2020). "Thus while males represent the highest proportion of individuals with severe G6PD phenotypes, there is also a comparable proportion of females with intermediate G6PD deficiency." (PMID 32766454, 2020). "Nevertheless, this use of primaquine is carried out regardless the knowledge of the frequency of the Glucose-6-phosphate-dehydrogenase (G6PD) deficiency among the target population, which endangers all the patients harbouring this deficiency with the risk of haemolysis." (PMID 32176714, 2020). "Glucose-6-phosphate dehydrogenase (G6PD) deficiency is a common hereditary disorder in China." (PMID 33051526, 2020). "In settings in which G6PD deficiency is prevalent, these efforts may result in greater cost-benefits beyond the use of G6PD tests for malaria treatment alone, and lead to more equitable malaria treatment." (PMID 32766454, 2020). "G6PD deficiency is common in malaria-endemic regions, an observation hypothesized to be due to balancing selection at the G6PD locus driven by malaria." (PMID 32536341, 2020). "Deleterious G6PD polymorphisms result in the most common human enzyme deficiency: G6PD deficiency." (PMID 32536341, 2020). "Indeed, the hematologic similarities between the diamide induced misshaped Fyn-/- mouse red cells associated with Hb oxidation and the blood smears from patients with G6PD deficiency during acute hemolytic crisis functionally connect Fyn and G6PD." (PMID 32863204, 2020). "G6PD deficiency was the least common of the traits investigated: 40/431 (9.3%) were female heterozygotes (G6PD(A)), while 24/431 (5.6%) males and 4/431 (0.9%) females were hemizygotes and homozygotes (G6PD(A-)), respectively." (PMID 33382828, 2020). "Recent renewed attention to the characterisation at a cellular level of heterozygous G6PD deficiency may help to raise awareness of the clinical implications of intermediate G6PD activity in females." (PMID 32766454, 2020). "We shipped samples diagnosed as disease or variant to Cincinnati Children’s Hospital in the United States of America for deoxyribonucleic-acid-based analyses to determine the prevalence of α-thalassaemia, glucose-6-phosphate dehydrogenase (G6PD) deficiency or fetal haemoglobin genetic modifiers." (PMID 33293746, 2020). "Allele frequency for the G6PD rs2230037 variant, associated with G6PD deficiency and hemolytic anemia, is around 10% for Serbian population, which is higher than in Finnish populations (5.6%), but lower in comparison to South Asians (27.8%) and Africans (26.7%)." (PMID 33312066, 2020). "However, 8-aminoquinoline drugs can cause severe drug-induced haemolysis in individuals with glucose-6-phosphate dehydrogenase (G6PD) deficiency." (PMID 32407682, 2020). "However, given the number of individuals whose G6PD were at the partially low normal range and the frequent detection of G6PD deficiency-related mutations, consistent monitoring of G6PD deficiency is needed." (PMID 32873296, 2020).
G6PD deficiency (continued). "The approach to diagnosing G6PD deficiency varies slightly between diagnostic laboratories and this may cause confusion to prescribers regarding a patient's G6PD status." (PMID 32036613, 2020). "In order to inform safer use of 8-aminoquinolines in the Greater Mekong Subregion, a multi-centre study was carried out to assess the prevalence of G6PD deficiency and to identify the main G6PD variants in samples collected in Cambodia, Lao PDR, Myanmar, Thailand and Vietnam." (PMID 30674319, 2019). "Vanuatu’s national guidelines recommended the routine testing of G6PD deficiency before PQ administration, and require clinical monitoring at higher level health facilities for patients with an unknown G6PD status at the time they received PQ treatment." (PMID 30786891, 2019). "This is the first study of World Health Organization–recommended weekly PQ therapy in Southeast Asia in which changes in the Hb level and other hemolytic markers over time are reported for patients with P. vivax malaria who have moderately severe G6PD deficiency or are G6PD normal." (PMID 31549159, 2019). "However, its routine use is difficult because of the hemolytic risk in patients with glucose-6-phosphate dehydrogenase (G6PD) deficiency." (PMID 30500927, 2019). "The current data, together with other published evidence, show that several populations in the GMS have high prevalence of G6PD deficiency and strongly indicate that safe use of 8-aminoquinolines for vivax malaria elimination will require qualitative and quantitative G6PD testing." (PMID 30674319, 2019). "Although there was a higher prevalence of G6PD deficiency among male children, the prevalence of P. vivax infections was similar among G6PD deficient individuals of both genders (13.6% vs. 8.8% by microscopy or RDT detection, 37.3% vs. 35.3% by qPCR detection)." (PMID 30922304, 2019). "Since 2016, Wuhan has increased the screening of erythrocyte glucose-6-phosphate dehydrogenase deficiency (G6PD, fluorescence assay) and congenital adrenal hyperplasia (CAH, time-resolved fluorescence) with a fully automated screening system and screened 42 genes using tandem mass spectrometry." (PMID 33072985, 2019). "Patients with G6PD activity that was less than 70% of this median, as determined on the basis of a quantitative spectrophotometric phenotype assay (Trinity Biotech), were considered to have G6PD deficiency and were excluded." (PMID 30650322, 2019). "G6PD deficiency can be caused by several mutations on the G6PD gene and the partial loss of enzymatic activity (i.e. deficiency) is associated with decreased capability of red blood cells to respond to oxidative stress (e.g. drug treatment, fever and ingestion of fava beans)." (PMID 30674319, 2019). "Understanding the distribution of G6PD deficiency in other geographical regions is recommended to inform the use of malaria intervention(s) such as primaquine that induces acute haemolytic anaemia in G6PD deficient individuals." (PMID 30819192, 2019). "Studies that have been conducted so far have focused on the prevalence of NH in G6PD-deficient neonates and shown that G6PD deficiency is one of the risk factors for NH in several populations or, at least, that G6PD-deficient neonates have significantly higher bilirubin levels than controls." (PMID 31862010, 2019). "However, the main disadvantage of FB is derived from its haemotoxicity, which can induce favism in individuals with glucose 6-phosphate dehydrogenase (G6PD) deficiency." (PMID 30823938, 2019). "However, primaquine causes acute haemolytic anaemia in patients with glucose-6-phosphate dehydrogenase (G6PD) deficiency." (PMID 30866940, 2019). "Due to the high prevalence of G6PD deficiency among people living in endemic areas, thorough and systematic G6PD screening is indispensable as the benefits could go beyond the context of malaria elimination." (PMID 30866940, 2019).
G6PD deficiency (continued). "In addition, this case provides further evidence on the prevalence and distribution of the G6PD Nilgiri in different population groups, confirming the high genetic heterogeneity of the G6PD deficiency in Italy, although owing to a de novo occurrence." (PMID 29333274, 2018). "The only drugs available that target all stages of the parasite can lead to severe side effects in patients with glucose-6-phosphate dehydrogenase (G6PD) deficiency; hence, there is an urgent need to develop new drugs active against blood and liver stages of the parasite." (PMID 29348637, 2018). "The CareStartTM G6PD deficiency RDT identified 13% (33/248) of participants as G6PD-deficient, with males showing a higher prevalence of G6PD deficiency (18%; 10/55) compared to females at 12% (23/193) (odds ratio 1.642; 95% confidence interval 0.7293–3.6992, P = 0.229)." (PMID 29558929, 2018). "However, in both the United States and Europe, migration makes it increasingly complicated to predict the prevalence of G6PD deficiency, the specific genotype, and the risk that certain newborn complications are related to G6PD status." (PMID 31709308, 2018). "Our biochemical and structural studies led us to determine whether improving the activity of G6PD variants with a pharmacological agent can provide a new therapeutic approach to reduce the risk of pathologies implicated in patients with G6PD deficiency." (PMID 30279493, 2018). "A total of 910 males were tested for the six most common G6PDd in SE Asia; and 30 (3.3%; 95% CI 2.1–5.1%) had a G6PD variant allele associated with G6PD deficiency, with the majority being the Union and Viangchan polymorphisms, with smaller numbers of Canton and Mahidol." (PMID 29859089, 2018). "Thus, quantitative G6PD tests in these populations can play a role in diagnosing G6PD deficiency more accurately in neonates." (PMID 29738562, 2018). "Among G6PD-d boys, 7 of 12 had SNPs at G202A, and 5 of 12 were identified as wild type, of whom 4 were characterized with partial G6PD deficiency and 1 was characterized with total G6PD deficiency, using semiquantitative testing." (PMID 29342267, 2018). "Most individuals with G6PD deficiency are clinically asymptomatic, but some G6PD variants could be lethal due to complete loss of enzyme activity." (PMID 29548282, 2018). "G6PD deficiency belongs to an X-linked recessive inborn error of metabolism that largely affects males (hemizygosity), whereas heterozygous females can be of normal, intermediate or deficient G6PD activity due to random chromosome X inactivation." (PMID 29339739, 2018). "Whilst the biochemical genetics of G6PD deficiency are well understood, data are scarce on the haemolytic effects of daily primaquine doses in G6PD heterozygous females with intermediate levels of G6PD activity (~ 30–80%), who would have a “normal” result using current G6PD deficiency rapid tests." (PMID 29499733, 2018). "Cost-effectiveness and cost-benefit studies on the introduction of routine G6PD testing in P. vivax-endemic settings, with complementary information on the local prevalence and genetic variants of G6PD deficiency will be critical in helping policymakers to prioritize limited resources." (PMID 28797255, 2017). "Another survey of hemoglobinopathies and G6PD deficiency in various ethnic groups living in Shan State of Myanmar detected the overall frequencies of α-thalassemia, HbE and G6PD-Mahidol at 37.5, 20.3 and 17.5%, respectively, and G6PD-Mahidol and HbE co-occurred in 2.8% of the population." (PMID 28531196, 2017). "In situations where blood transfusions are not accessible, further information may be required on the prevalence of G6PD deficiency and associated risk of hemolysis in females with intermediate G6PD deficiency who test normal by current G6PD RDT methods." (PMID 28542194, 2017). "G6PD deficiency was observed in 26 (26.3%) out of 99 patients whose G6PD levels were measured." (PMID 28875002, 2017).
G6PD deficiency (continued). "In summary, the clinical manifestations observed in individuals with G6PD deficiency could be attributable to two major causes: the reduction in the catalytic activity of the G6PD variants or the decrease in the number of active G6PD molecules." (PMID 28583873, 2017). "However, in none of these cases did hemoglobin fall by ≥ 2 g/dL, or to below 7 g/dL and G6PD genotyping, possible in five cases, indicated only wild-type alleles at the Mediterranean G6PD deficiency locus." (PMID 29141719, 2017). "As G6PD deficiency can be clinically silent until illness strikes, we recommend investigation of the possible benefits of screening for the G6PD genotype along with using HbA1c to diagnose T2D in populations of African ancestry or groups where G6PD deficiency is common." (PMID 28898252, 2017). "Primaquine is the only drug currently licensed for the radical cure of P. vivax; however, it can cause severe hemolysis in individuals with glucose-6-phosphate dehydrogenase (G6PD) deficiency, a common genetic disorder that is positively associated with P. vivax incidence." (PMID 28542194, 2017). "Results showed G6PD deficiency in 26 (26.3%) and normal G6PD level in 73 (73.7%) patients." (PMID 28875002, 2017). "The dosage required for these drugs to be effective curative agents for P. vivax infection may cause severe hemolysis in patients with glucose-6-phosphate dehydrogenase (G6PD) deficiency." (PMID 28552983, 2017). "The degree of phenotypic G6PD deficiency (G6PDd) depends on the genetic variant and the zygosity of the carrier, and it is most commonly due to an instability of the G6PD enzyme or an altered functionality of the protein active site expressed in mature erythrocytes." (PMID 28591790, 2017). "The parents should carry the allele conferring G6PD deficiency, and some exhibited decreased, albeit only slightly, G6PD activity, led to the GSH concentrations and GSH/GSSG ratios in the parent group were higher than patient group and lower than the normal control group." (PMID 28728551, 2017). "Understanding the molecular mechanisms underlying the severity of G6PD deficiency is of great importance but that of many G6PD variants are still unknown." (PMID 28583873, 2017). "However, countries in sub-Saharan Africa have been reluctant to use primaquine due to a lack of evidence about safety of the low-dose regimen in individuals with glucose-6-phosphate dehydrogenase (G6PD) deficiency." (PMID 28605472, 2017). "We use an experimental approach to determine whether G6PD-MahidolG487A variant, a widespread cause of severe G6PD deficiency in Southeast Asia, provides a barrier against vivax malaria." (PMID 28591790, 2017). "It has been argued that the >6% of the individuals with severe G6PD deficiency necessitates G6PD screening before the prescription of primaquine, whereas the HbEE may lead to an increased risk of uncomplicated malaria." (PMID 28531196, 2017). "In sub-Saharan Africa, G6PD deficiency is usually due to the G6PD (A-) allele." (PMID 28605472, 2017). "Due to the scarcity of hospitals providing this service and the realization of the importance of G6PD activity measurement as part of strategy of prevention of severe neonatal jaundice associated with G6PD deficiency, UKMMC laboratory has offered this service to other hospitals." (PMID 27103895, 2016). "Therefore, further studies are needed to explore the best performance conditions of the CareStartTM G6PD RDT for detecting G6PD deficiency among Yemeni people." (PMID 27329471, 2016). "Moreover, a lower susceptibility to cardiovascular disease has been described in patients with G6PD deficiency, while mice with genetic deficiency in G6PD are protected against atherosclerosis." (PMID 27245224, 2016).
G6PD deficiency (continued). "On the other hand, the sensitivity of the CareStartTM G6PD RDT ranged from 81.3 % (95 % CI 68–90 %) to 97.4 % (95 % CI 78–100 %) for detecting G6PD deficiency at the cut-offs of ≤60 and ≤30 %, respectively, compared to the reference method, with comparable specificity levels of 96.4–96.9 %." (PMID 27329471, 2016). "In our study, infants with G6PD deficiency are at an increased risk for hyperbilirubinemia in the first few days of life even in the hospital free from agents that can potentially cause destruction of G6PD-deficient red cells." (PMID 27557546, 2016). "In addition, comparable PPVs and NPVs of 74–78 and 97.4–99.7 %, respectively, were found for detecting G6PD deficiency using the CareStartTM G6PD RDT compared to the reference method at the cut-off activities of ≤30–60 % of normal G6PD activity." (PMID 27329471, 2016). "Interestingly all other participants suffering from mild G6PD deficiency suffered from a P. falciparum mono-infection, all participants receiving 14DPQ where classified as G6PD normal." (PMID 27128675, 2016). "This could be due to a low prevalence of G6PD deficiency in this malaria-infected population or due to a multitude of factors that affect the performance of G6PD tests." (PMID 27450652, 2016). "G6PD variants are generally classified according to the severity of the G6PD deficiency that accompanies the enzyme activity and hematological parameter of the patients, ranging from the most severe manifestations with less than 5% residual activity (Class I) to the mildest form (Class V)." (PMID 27941691, 2016). "Interestingly, the prevalence of G6PD deficiency correlates with the geographical distribution of malaria, leading to postulate that G6PD deficiency gives a partial protection against this infection." (PMID 27941691, 2016). "Instead, the G6PD Mediterranean563T, a C → T substitution leading to an amino acid change Ser → Phe at position 188, responsible for a severe form of G6PD deficiency, is widely distributed across southern Europe, the Middle East, through Iran, Afghanistan, Pakistan, and much of western India." (PMID 26753754, 2016). "One patient had glucose-6-phosphate dehydrogenase (G6PD) deficiency." (PMID 27316351, 2016). "Although only four alleles have been found to be associated with G6PD deficiency in African populations (G6PD c.202T, G6PD c.542A, G6PD c.680T, and G6PD c.968C32, 33), studies have not been exhaustive and other alleles might remain to be discovered." (PMID 26686045, 2015). "G6PD deficiency is an X-linked inherited disorder that results from mutations in the G6PD gene." (PMID 25775246, 2015). "The elimination effort may further be complicated by possible glucose-6 phosphate dehydrogenase (G6PD) deficiency which would hinder the use of 8-aminoquinolines in the elimination efforts." (PMID 26242243, 2015). "Whether females and/or males are protected by G6PD deficiency is uncertain, due in part to G6PD and malaria phenotypic complexity and misclassification." (PMID 25671784, 2015). "Malaria programmes expressed safety concerns of SLD primaquine use in individuals with glucose-6-phosphate dehydrogenase (G6PD) deficiency, as well as potential interactions between primaquine and co-morbidities, and drug-drug interactions with HIV and/or tuberculosis treatments." (PMID 25971688, 2015). "The overall prevalence of G6PD deficiency (partial and full defect) in this study was 19.3% (2.3% full defect, 17% G6PD partial defect) and G6PD deficiency across the country was comparable as about the same proportions of women in the three main ecological zones (18–22%) were G6PD deficient." (PMID 26327623, 2015). "G6PD gene is extraordinarily polymorphic with more than 400 variants discovered based on biochemical diagnosis, among which 186 mutations are associated with G6PD deficiency." (PMID 26226515, 2015).